NSD1 (nuclear receptor binding SET domain protein 1)
Diseases named in the same sentence as NSD1 in open-access papers (continued):
Sharing a sentence is not in itself a finding about the gene and the disease.
cancer (continued). "Overall, the mechanism by which NSD1 regulates cancer cell growth and therapeutic response is complex, and not fully understood." (PMID 37786686, 2023). "Furthermore, compared to NSD1 and −2, we find that genetic variation and amplification to NSD3 is most prevalent in cancer." (PMID 37062069, 2023). "Other avenues in cancers where NSD1 displays a protumoral role include proteolysis targeting chimeras (PROTAC) technology, which utilizes the ubiquitin-protease system to target a specific protein, here NSD1, and induce its cellular degradation." (PMID 36230787, 2022). "According to Cancer Genome Interpreter (CGI) analysis, alterations in SETD2, BAP1, FLT4 and PTEN genes were reported as known drivers in several tumor types, and events in FGFR4 and NSD1 genes were classified as predicted drivers." (PMID 33668731, 2021). "Concerning additional cancer genes identified in the significantly altered regions, some were characterized as known drivers (SETD2, BAP1, FLT4 and PTEN) and others as predicted drivers (FGFR4 and NSD1), according to the CGI." (PMID 33668731, 2021). "Interestingly, we observed statistical significance for the loss of internal degrons from several fusion genes, such as 5′ EML4 fusions, 3′ NSD1 fusions and the previously validated 3′ ETV4 fusions, only when considered in conjunction with cancer type." (PMID 34795215, 2021). "Five of the pan-cancer ALFRED genes (BRCA1, ATM, BRCA2, NSD1, and TPCN2) were individually significantly enriched for RDGVs in cases versus controls (P < 0.05 by pan-cancer case-control analysis) with one additional gene, NIPAL3, marginally significant (P = 0.07 by case-control analysis)." (PMID 29973584, 2018). "However, the results show that the higher expression of NSD1 was not present in the initial cancer stage (stage I), only in stages II, III and IV." (PMID 32153656, 2020). "Conversely, perturbations that may promote aberrant stem cell-like activity and impair differentiation (cancer-promoting genes) included bromodomain-containing proteins (BRD1, BRD2), histone acetyltransferases (EP300), and histone lysine methyltransferases (KMT2C, NSD1, SETD1B)." (PMID 38472198, 2024). "Co-occurring of genetic mutations in cancers with KDM5C alterations were not uncommon in both early-stage and advanced stage cohort and some of them are prevalent driver genes (e.g., LRP2, KMT2C, PBRM1, NOTCH1, FAT1, SETD2, NSD1, etc.), while their clinical significance remained undetermined." (PMID 33953726, 2021). "However, the effects of other frequent missense cancer mutants in NSD2 and its paralog NSD1 are not well understood." (PMID 37150325, 2023).
tumor (72 papers, 2007 to 2025). "By contrast, the advantage of gaining NSD1 mutations during tumor evolution is most probably due to crosstalk with immune-regulatory pathways resulting in immune exclusion." (PMID 40082664, 2025). "Multi-omics analyses also identified NSD1 as one of the genes positively correlated with tumor mutation burden (TMB), a predictive biomarker for immunotherapy response." (PMID 41301842, 2025). "Altogether, these data support the view that tumors with impaired H3K36 methylation and in particular damaging NSD1 mutations build a less aggressive tumor subtype of HPV-negative HNSCC less prone to metastasize." (PMID 40082664, 2025). "Analyzing the clinicopathological tumor characteristics, NSD1 mutations were more frequent in tumors of smokers (P = 0.002), associated with the absence of nodal metastasis (P = 0.002), and associated with tumor localization in the larynx (P = 0.0001)." (PMID 40082664, 2025). "In biochemical experiments, we show here that the NSD1 mutations Y1971C, R2017Q, and R2017L observed mostly in solid cancers are catalytically inactive suggesting that NSD1 acts as a tumor suppressor gene in these tumors." (PMID 37150325, 2023). "Immune checkpoint inhibitors are showing great promise in numerous tumor types; however, HNSCC tumors with inactivating NSD1 mutations have an “immune cold” microenvironment, characterized by the reduced infiltration by tumor-associated leukocytes." (PMID 37786686, 2023). "Somatic variants affecting NSD1 have been identified in various types of tumors, suggesting a potential tumor suppressing role." (PMID 37384309, 2023). "Somatic disruption of NSD1 has been implicated in multiple tumor types, particularly hematological malignancies." (PMID 36230787, 2022). "Patients #3 and #4 were carriers of the novel NSD1 variant c.5993T > A (p.Met1998Lys), but exclusively in the primary tumor." (PMID 36611369, 2022). "Only one of the 20 CRCs had an acquired somatic mutation in the corresponding gene, which corresponded to a tumor from an NSD1 variant carrier." (PMID 35158968, 2022). "Despite improved prognosis, NSD1 mutation in HPV- HNSCC has been associated with an immunologically “cold” tumor microenvironment associated with slightly low levels of TILs." (PMID 33588906, 2021). "Among all primary tumor samples, the most commonly mutated gene was NSD1, affected in 9/31 patients." (PMID 31500094, 2019). "We also found cases with pathogenic variants in the ClinVar database, including in PTEN and NSD1, suggesting potential adnexal tumor predisposition alleles." (PMID 31101826, 2019). "Furthermore, inactivating mutations in NSD1 can inhibit tumor growth, decrease methylation, and reduce immune infiltration." (PMID 40475768, 2025). "According to the reported involvement of NSD1 in tumorigenesis, our study may help to clarify which distinct pathways of genes associated to tumor are specifically regulated by different NSD1 isoforms." (PMID 39336709, 2024). "In addition to affecting tissue growth and development, NSD1-mediated histone methylation is also associated with tumor formation." (PMID 38719811, 2024). "In addition, NSD1 is inactivated in certain types of tumors, resulting in an immune-cold phenotype characterized by a low infiltration of tumor-associated leukocytes, suggesting a potential association between NSD1 and immune disturbances." (PMID 37176149, 2023). "Interestingly, the NSD1 variant (c.5924T > A; p.Leu1975His) was also identified in the recurrent tumor of patient #1." (PMID 36611369, 2022). "Another explanation is also related to immunogenicity as the higher mutational load detected in NSD1-mutant tumors may favor immune recognition and tumor elimination." (PMID 36230787, 2022). "Interestingly, tumors formed by lung cancer cell lines with shRNA-mediated reduced NSD1 expression in immunodeficient mice contained also less tumor-infiltrating T cells and were associated with reduced expression of various cytokines and chemokines." (PMID 34575025, 2021).
tumor (continued). "Further, the NSD1 subtype of HNSC displays an ‘immune cold’ phenotype characterized by low infiltration of tumor-associated leukocytes, particularly macrophages and CD8+ T cells, as well as low expression of genes encoding the immunotherapy target PD-1 immune checkpoint receptor and its ligands." (PMID 29213088, 2017). "This epigenetic silencing of immune effector genes contributes to the immune-cold tumor microenvironment often observed in NSD1-mutant HNSCC." (PMID 40586874, 2025). "Nuclear receptor-binding SET domain-containing protein 1 (NSD1) inactivation in tumor cells contributes to an immune-cold phenotype, indicating its potential association with immune disturbances." (PMID 37176149, 2023). "Further, a recent publication has used multiple in vivo and in vitro models to show that depletion of NSD1 leads to tumor immune evasion in HNSCC." (PMID 37786686, 2023). "In vivo, WNT10B knockdown and NSD1 knockout were sufficient to reduce tumor volume and weight, and the combination knockdown/knockout further suppressed tumor volume and weight and reduced pulmonary metastasis significantly." (PMID 36814601, 2023). "Specifically, NSD1 acts as an apparent tumor suppressor, whereas NSD2 primarily promotes oncogenesis." (PMID 37602556, 2023). "Preclinical studies have identified both oncogenic and tumor-suppressing properties across NSD1, NSD2, and NSD3 within the context of HNSCC." (PMID 36360250, 2022). "In summary, NSD1 silencing inhibits tumor growth by inhibiting the Wnt/β-catenin signaling pathway activation." (PMID 35200072, 2022). "The novel NF1 variant (c.6361T > G (p.Ser2121Ala) and NSD1 variant (c.5924T > A; p.Leu1975His), occurring within the highly conserved SET domain, were instead exclusively identified in the recurrent tumor." (PMID 36611369, 2022). "The novel NSD1 variant c.5924T > A (p.Leu1975His), occurring within the highly conserved SET domain, was exclusively identified in the recurrent tumor in patient #1 and in the primary tumor in patients #2, #3 and #4." (PMID 36611369, 2022). "In human HCC, NSD1 expression is higher in tumor tissues relative to normal tissue and its expression is associated with a reduced overall survival." (PMID 36230787, 2022). "KB-68A7.1 functions as a tumour suppressor via binding to and sequestrating NSD1 in the cytoplasm, reducing WNT10B transcription, and repressing Wnt/β-catenin signalling." (PMID 35127520, 2021). "KB-68A7.1 has tumour-suppressive roles via binding to NSD1, sequestrating NSD1 in the cytoplasm, and repressing Wnt/β-catenin signalling." (PMID 35127520, 2021). "It is an important partner of NSD1 gene, acts as a tumor suppressor and a key regulator of genome stability." (PMID 31500094, 2019). "Collectively these results demonstrate that silencing Wnt10b in combination with NSD1 knockout imposes a significant blockade in the Wnt/β-catenin signaling pathway, and thereby strongly inhibits tumor formation as well as extent of metastatic lesions in vivo." (PMID 31727171, 2019). "Strikingly, silencing Wnt10b in combination with a knockout of NSD1, further suppressed the volume and weight of xenograft tumor in nude mice." (PMID 31727171, 2019). "We demonstrate that NSD1 inactivation induces immune cell exclusion from the tumor microenvironment using an in vivo mouse model of tumor immune infiltration, recapitulating the immune cold phenotype observed in the analysis of the TCGA data." (PMID 29213088, 2017). "Univariate analysis data indicated that the PRB4 level (P=0.013) and NSD1 level (P=0.010), as well as the tumor size (P=0.027), metastasis (P=0.006), and clinical stage (P=0.008) was significantly associated with the survival." (PMID 29156722, 2017). "To assess a potential functional role of NSD1 inactivation in the exclusion of immune cells from the tumor microenvironment, we inhibited the expression of NSD1 by shRNA transduction in three established HNSC cell lines, PCI-13, FaDu, and UM-SCC-6." (PMID 29213088, 2017).
tumor (continued). "We have found intriguing evidence that NSD1 inactivation promotes immune evasion by the exclusion of immune cell infiltration into the tumor microenvironment." (PMID 29213088, 2017). "Using an in vivo model, we demonstrate that NSD1 inactivation results in reduced T cell infiltration into the tumor microenvironment, implicating NSD1 as a tumor cell-intrinsic driver of an immune cold phenotype." (PMID 29213088, 2017). "There was a significant reduction in the expression of several key chemokines associated with knocking down NSD1 in HNSC cell lines, indicating that NSD1 contributes to the regulated expression of these genes in the tumor cells." (PMID 29213088, 2017). "A number of histone methyltransferases, including Setd3, Setd5, Suv39h2, Smyd3, Prmt3, Prmt6, Nsd1, and Nsd2, were up-regulated in metastases compared to disseminated tumor cells or primary tumors." (PMID 23520493, 2013). "In several solid tumors, tumor-promoting roles of NSD1 have also been reported." (PMID 41301842, 2025). "While no direct evidence for regulation of tumor metastasis by NSD1, altered NSD1 expression has been associated with occult lymph node metastasis in patients with HNSCC." (PMID 41301842, 2025). "In contrast, additional evidence supports tumor-suppressive functions of NSD1." (PMID 41301842, 2025). "NSD1 mutations are an example of a spatial constant tumor-specific determinant of TB that is not influenced by tumor heterogeneity." (PMID 40082664, 2025). "For instance, AURKA inhibitors, effective in RB1 and PTEN mutant tumours, could be trialed in tumours with mutations in less-studied tumour suppressors, such as FBXW7 and NSD1, for which we found AURKA to be a key gene in classification." (PMID 40775769, 2025). "Additionally, we identified AURKA inhibitors as potential therapeutic option for tumours with alterations in tumour suppressors like FBXW7 or NSD1." (PMID 40775769, 2025). "Notably, treatment with an EZH2 inhibitor restores immune cell infiltration and inhibits tumor growth in NSD1-mutant models, highlighting a druggable chromatin crosstalk with potential therapeutic relevance." (PMID 40586874, 2025). "Several previous studies have shown an important role for NSD1 in anti-tumor immunity." (PMID 40586874, 2025). "The inactivation of this transcriptional regulator led to decreased infiltration of T cells even in a mouse model, as the authors applied NOD-scid IL2Rgammanull (NSG) mouse to establish tumor of control or NSD1 shRNA and human peripheral blood mononuclear cell (PBMC) injection." (PMID 38540967, 2024). "Ideally, the SET domains of NSD1/2 could be targeted with inhibitors to reduce tumor growth, but such efforts have proven unsuccessful on a nanomolar scale." (PMID 39765675, 2024). "Excitingly, NSD1 depletion resulted a dramatic suppression of tumor growth." (PMID 37786686, 2023). "NSD1 regulates H3K36me2 level along with cell proliferation and tumor growth in HNSCC." (PMID 37786686, 2023). "NSD1 is a bifunctional transcriptional regulatory protein able to participate in the regulation of mono- and dimethylation of H3K36, and targeting NSD1 may be a potential strategy for tumor therapy." (PMID 37179342, 2023). "In conclusion, depending on the cellular context, and the chromatin modifying alterations, NSD1 may function then, as either an oncogene or as a tumor suppressor." (PMID 36230787, 2022). "While NSD1 expression varies across tumor types, its enzymatic activity might also differ across tumor types." (PMID 36230787, 2022).
tumor (continued). "Additionally, analysis of xenograft formed with NSD1-knocked down LUSC cells revealed immune cell exclusion within the tumor microenvironment compared to the wild-type LUSC cells." (PMID 36230787, 2022). "Depending on the cellular context, NSD1 exerts tumor suppressive or promoter effects." (PMID 36230787, 2022). "NSD1 exerts tumor suppressive or promoter functions depending on the cellular context." (PMID 36230787, 2022). "Furthermore, NSD1 silencing promoted paclitaxel sensitivity of paclitaxel-resistant BC cells and suppressed tumor growth and paclitaxel resistance in vivo." (PMID 34905470, 2021). "Thus, a possible connection between NSD1 expression and T-cell infiltration into the tumor microenvironment appears unique to HPV- HNSCC samples and is not shared with the other NSD paralogs." (PMID 33588906, 2021). "Given that NSD1 and NSD2 have been linked to various aspects of HPV- HNSCC, including epigenetic alterations, immune status of the tumor, and predicting patient outcome at specific subsites, we investigated the roles of NSD1 and its two paralogs NSD2 and NSD3 in HPV+ HNSCC." (PMID 33588906, 2021). "Furthermore, weak T-cell infiltration was also associated with decreased NSD1 expression in other patient-derived datasets for HPV- tumors and experimental tumor models with HPV- HNSCC cells." (PMID 33588906, 2021). "Additionally, it was confirmed that depletion of NSD1 inhibited BC tumor proliferation, EMT as well as paclitaxel resistance in vivo." (PMID 34905470, 2021). "Will such NSD1-SET inhibitors also block NSD1’s role as a tumor suppressor?" (PMID 34575025, 2021). "Multiple studies suggest that NSD1 can act as a tumor suppressor gene." (PMID 32533074, 2020). "Notably, 2 paired epithelial and mesenchymal samples from one tumour presented with convergent mutations of SETD2 and NSD1, which have been described to be associated with an aggressive phenotype in ccRCC9." (PMID 31959902, 2020). "Finally, using a xenograft nude mouse model we demonstrated that knockout of NSD1 suppresses the expression of Wnt10b, thus inhibiting the proliferation and migration of tumor cells in vivo by inactivating the Wnt/β-catenin signaling pathway." (PMID 31727171, 2019). "Here, we characterize NSD1 mutations from the expanded The Cancer Genome Atlas (TCGA) HNSCC cohort (n = 522) and examine their prognostic implications based on HPV status of the tumor." (PMID 31321084, 2019). "Thus, our data support a role of NSD1 as a tumor cell-intrinsic determinant of T cell infiltration into the tumor microenvironment." (PMID 29213088, 2017). "Such immune regulators may include potential drug targets to restore anti-tumor immunity in NSD1 inactivated HNSCs." (PMID 29213088, 2017). "Additionally, two pathogenic variants in the NSD1 gene appeared in a significant percentage of cells in the primary but not in the relapsed tumor, suggesting tumor evolution or selection." (PMID 39273494, 2024). "In this study, we examined whether ectopic overexpression of NSD, the Drosophila homolog of human NSD1, disturbs innate immunity, since deregulation of the immune system due to the loss-of-function of NSD1 has been reported in SOTOS patients and certain types of human tumor cells." (PMID 37176149, 2023). "Therefore, in this study, we tested the hypothesis that elevated levels of NSD1 may be oncogenic and could promote tumor progression in HPV-negative HNSCC." (PMID 37786686, 2023). "Thus, in specific settings targeting NSD1 or its downstream effectors may be a potential strategy for tumor therapy." (PMID 36230787, 2022). "Moreover, in vivo experiments suggested that NSD1 silencing repressed tumor growth." (PMID 35200072, 2022).